NUCB2 (nucleobindin 2)
Diseases named in the same sentence as NUCB2 in open-access papers (continued):
Sharing a sentence is not in itself a finding about the gene and the disease.
tumor (continued). "Moreover, tumor size (P < 0.001), pT stage (P = 0.012), Fuhrman grade (P < 0.001), tumor necrosis (P = 0.001) and NUCB2 expression (P = 0.018) were demonstrated as independent prognostic indicator in validation cohort with CSS." (PMID 27806328, 2017). "The result showed NUCB-2 suppression also reduced the number of tumor nodules." (PMID 27150059, 2016). "Furthermore, the intrinsic vascular permeability characteristic of GBM may facilitate the selective accumulation of suitably engineered therapeutics, thereby enabling targeted modulation of NUCB2 within the GBM tumour microenvironment." (PMID 40913484, 2025). "Several plausible mechanisms merit consideration: NUCB2 may modulate the production of immunosuppressive cytokines or metabolites that remodel the local tumour microenvironment, thereby fostering conditions conducive to T‐cell dysfunction despite robust transcriptional activation." (PMID 40913484, 2025). "Furthermore, we investigated whether NUCB-2/nesfatin-1 could affect the tumor development in NPC cell line and serve as a potential biomarker for NPC diagnosis and treatment." (PMID 37635259, 2023). "Therefore, by interacting with different partners, NUCB2/NESF-1 may be involved in tumor development." (PMID 34361082, 2021). "Furthermore, we investigated whether nesfatin-1/NUCB-2 affected the tumor development in a murine tumor model and served as a potential biomarker of metastasis in an online microarray dataset." (PMID 27150059, 2016). "Collectively, these findings identify NUCB2 as a critical regulator of GBM cell proliferation, corroborating its elevated expression in tumour tissues and underscoring its potential as a therapeutic target in GBM." (PMID 40913484, 2025). "Functional characterisation demonstrated NUCB2's critical role in regulating GBM stem cell proliferation, with knockdown experiments resulting in significant reduction in tumour cell growth." (PMID 40913484, 2025). "Specifically, NUCB2, SCGN and IFI6 were markedly upregulated in cells from the tumour centre, whereas COL5A2 was significantly downregulated in this region." (PMID 40913484, 2025). "In summary, our study identifies NUCB2 as a multifaceted regulator in GBM, orchestrating both proliferative capacity and immunomodulatory functions that collectively contribute to tumour progression." (PMID 40913484, 2025). "To confirm the role of NUCB2-dependent HMGCR and SREBP2 expression in tumor metastasis in vivo, we performed immunohistochemical staining on metastatic lung tissues of nude mice." (PMID 37277807, 2023). "Some proteins, such as metalloproteinase inhibitor 1 (TIMP1), 78 kDa glucose‐regulated protein (GRP78), nucleobindin‐2 (NUCB2), and calbindin (CALB1), were found to be significantly changed in only the tumor‐rejecting rats." (PMID 31090175, 2019). "The analysis revealed that in the training set, the expression of BANF1, CDK2AP2, DDT, LRIG1, MRPL4, and S100A13 was significantly upregulated in tumor samples, and the expression of EPS8, NUCB2, PAF1, PMP22, RABGAP1L, and USO1 was higher in control samples (p < 0.05)." (PMID 41000388, 2025). "Tumour regions enriched with NUCB2‐expressing NPC‐like populations may exhibit enhanced sensitivity to such targeted therapies, whereas areas dominated by NUCB2‐low cellular subsets could maintain their resistance to treatment." (PMID 40913484, 2025). "In the future, we can screen corresponding antibodies and inhibitors targeting NUCB2/mTORC1/SREBP2/Cholesterol pathway, which inhibit tumor metastasis in vivo, resulting in laying a foundation for the development of therapeutic drugs related to translational medicine." (PMID 37277807, 2023). "NUCB2/NESF1 as the protein with many functional domains may interact with different partners and can be involved in tumor progression." (PMID 36012443, 2022). "It indicates that NUCB-2 overexpression in tumor does not result in elevation of nesfatin-1 in serum." (PMID 27150059, 2016).
tumor (continued). "The immunofluorescent staining showed the expression NUCB-2 in tumor was higher than that in non-tumor regions." (PMID 27150059, 2016). "The expression of NUCB-2 in tumor regions is higher than that in non-tumor regions." (PMID 27150059, 2016). "Thus, we presume that NUCB-2 can enhance occurrence and development of NPC rather than promote metastasis or invasion of the tumor." (PMID 37635259, 2023). "The result may suggest NUCB-2 promotes tumor EMT via autocrine and paracrine pathways while the NUCB-2-derived-nesfatin-1 is not sufficient to elevate the serum concentration of nesfatin-1." (PMID 27150059, 2016).
cancer (25 papers, 2002 to 2026). A tumor composed of atypical neoplastic, often pleomorphic cells that invade other tissues. "NUCB2 is implicated in various stages of cancer progression, where it facilitates tumorigenesis, invasion, migration, and epithelial-mesenchymal transition (EMT) of cancer cells." (PMID 37830634, 2023). "Nucleobindin 2 (NUCB2) is another decreased factor that is associated with cancer and affects keratinocyte migration in wound healing by its fragment." (PMID 33916959, 2021). "Moreover, high expression of NUCB2/nesfatin-1 is associated with key traits of cancer as well as poor prognoses and outcomes." (PMID 36585713, 2022). "In general, the expression of NUCB2/NESF-1 is associated with cancer progression." (PMID 34361082, 2021). "In addition to its physiological role, Nucb2/nesfatin-1 is also associated with pathological states, such as carcinoma development." (PMID 34073612, 2021). "Recent studies have suggested that NUCB2/nesfatin-1 plays a significant role in cancer development and progression." (PMID 40964608, 2025). "Previous studies have suggested that the role of NUCB2 in cellular proliferation and stress responses in different cancers; however, a comprehensive functional understanding in the context of brain malignancies is notably lacking currently." (PMID 40913484, 2025). "A comprehensive pan‐cancer analysis revealed that NUCB2 expression is markedly elevated in various cancer types compared to their corresponding normal tissues." (PMID 40913484, 2025). "Further research is needed to better understand the abnormal expression of NUCB2/nesfatin‐1 and utilize it as a potential target in cancer therapy." (PMID 36065769, 2022). "Collectively, it is rational to assume that the role of NUCB2/nesfatin‐1 in cancers is variable and tissue‐specific." (PMID 36065769, 2022). "Nesfatin‐1, a newly discovered adipokine derived from nucleobindin‐2 (NUCB2), has been described as a new prognostic marker in cancers." (PMID 36065769, 2022). "The current review is the first to present NUCB2/NESF-1 as a potential new prognostic or predictive marker in cancers." (PMID 34361082, 2021). "Here we summarize available data about NUCB2/NESF-1 expression in relation to clinicopathological properties in different cancer types." (PMID 34361082, 2021). "According to the latest findings, nucleobindin-2/nesfatin-1 (NUCB2/NESF-1) is an important factor in cancer development and progression." (PMID 34361082, 2021). "Still, the control of Nucb2/nesfatin-1 activity in cancer progression requires further investigation." (PMID 34073612, 2021). "It was also shown that FTX/Nucb2 accelerated the metastasis of cancer through mediation in the phosphorylation of protein kinase B and mTOR." (PMID 34073612, 2021). "In most cases, Nucb2 expression was correlated with the key clinicopathological characteristics of cancer." (PMID 34073612, 2021). "It is worth noting that Nucb2/nesfatin-1 not only stimulates cancer progression, but also influences the life quality of patients, in turn leading to decreased treatment success." (PMID 34073612, 2021). "FTX played an oncogenic role in LUAD and contributed to cancer development via targeting miR-335-5p/NUCB2 axis." (PMID 32226311, 2020). "Through starBase (an online tool), NPC2, LRRC8A and NUCB2 were predicted with the strict condition (pan-cancer ≥ 8; degradome data ≥ 3 and clip data ≥ 5)." (PMID 32226311, 2020). "Patients with high NUCB2 mRNA transcription level (P = 0.005) and protein expression level (P = 0.024 and P < 0.001, respectively) had shorter cancer-specific survival in Kaplan-Meier survival curve." (PMID 27806328, 2017). "Nevertheless, three-nucleotide deletion within the coding region of NUCB2 that we detected with very high frequency among the cancer patients, is very interesting finding." (PMID 12087473, 2002). "Increasing evidence highlighted that NUCB2 is an important regulator in several cancers." (PMID 39309426, 2024).
cancer (continued). "Finally, we suggest a link between NUCB2, E-cadherin, and the epithelial to mesenchymal transition (EMT), which is a hallmark of cancer associated with reduced apoptosis and increased invasiveness." (PMID 38760405, 2024). "Little is known about the mechanism of action of NUCB2 in cancer cells." (PMID 36012443, 2022). "Specifically, it has been demonstrated that NUCB2 contributes to cancer metastasis and a number of related processes, including EMT, endoplasmic reticulum (ER) stress, and cancer anorexia-cachexia syndrome, through regulation of the LKB1/AMPK/TORC1/ZEB1 and Akt/mTOR pathways." (PMID 36585713, 2022). "Accumulating evidence indicates that NUCB2/NESF-1 is a new cancer-related protein." (PMID 36012443, 2022). "NUCB2 expression in the cytoplasm of cancer cells was found in 406 IDC cases (91%)." (PMID 36012443, 2022). "Considering that NUCB2/nesfatin‐1 is an important factor in cancer development and progression, the aim of the present study was to investigate whether NUCB2/nesfatin‐1 was involved in the cell proliferation, migration and invasion in GC." (PMID 36065769, 2022). "To conclude, the role of NUCB2/NESF-1 in cancers is variable and tissue-specific." (PMID 36012443, 2022). "NUCB2/nesfatin-1 has also been proposed to play a role in cancer progression by enhancing proliferation, migration, invasion, and evasion of apoptosis in most cancer types although few studies report that NUCB2/nesfatin-1 inhibits cell proliferation and increases apoptosis." (PMID 36499229, 2022). "This phenomenon resulted in a higher expression of NUCB2 and promotion of cancer cell progression." (PMID 34361082, 2021). "Further studies also revealed that Nucb2 is involved in cancer progression and metastasis." (PMID 34073612, 2021). "NUCB2/NESF-1 is considered both cancer suppression and progression factors." (PMID 34361082, 2021). "Moreover, it was also demonstrated that patients with high NUCB2/NESF-1 expression had a shorter cancer-specific survival rate." (PMID 34361082, 2021). "Additionally, patients with colon carcinomas with TNM Classification of Malignant Tumors of stages III-IV have an increased expression of Nucb2 when compared with patients with stages I-II." (PMID 34073612, 2021). "To summarize, NUCB-2 seems to play an important role in cancer progression." (PMID 34361082, 2021). "The analysis of the expression level of Nucb2 might be utilized in cancer therapy monitoring, as well as provide independent information alongside known biomarkers, such as PSA." (PMID 34073612, 2021). "To summarize, NUCB2 seems to be an important factor in cancer cell migration and invasion and may affect the expression of MMP-2 and MMP-9." (PMID 34361082, 2021). "The immunoreactivity of Nucb2 was mainly detected in the cytoplasm of cancer cells." (PMID 34073612, 2021). "In general, the expression of NUCB2 in cancers is significantly higher compared to normal control." (PMID 34361082, 2021). "Currently, little is known about the NUCB2/NESF-1 mechanism of action in cancer cells." (PMID 34361082, 2021). "Recent studies show the role of NUCB2 in the EMT of cancer cells." (PMID 34361082, 2021). "In addition, NUCB2/NESF-1 seems to be an independent prognostic factor for cancer-specific survival in ccRCC." (PMID 34361082, 2021). "Moreover, multivariate analysis identified NUCB2 expression level as an independent prognostic factor for cancer-specific survival." (PMID 27806328, 2017). "Nasfatin-1/NUCB-2 shows diverse function in different types of tissues and cancers." (PMID 27150059, 2016). "This evidence suggests that NUCB-2 can induce metastasis in some types of cancer." (PMID 27150059, 2016). "Prior studies on members of a newly identified family of non-receptor guanine nucleotide exchange factors (GEFs), GIV/Girdin, Daple, NUCB1 and NUCB2 have revealed that GPCR-independent hyperactivation of trimeric G proteins can fuel metastatic progression in a variety of cancers." (PMID 26916336, 2016).
cancer (continued). "In addition, serological responses to seven antigens (including TACC1, NUCB2, Tbdn-1 and granulin etc.)were restricted to cancer patients and investigation of their relevance for sero-diagnosis or prognosis is in progress." (PMID 12087473, 2002). "Interestingly, in both presented cases, Nucb2 impacts cancer progression via the mTOR pathway." (PMID 34073612, 2021). "This feature may be crucial for understanding NUCB2 regulation in different cancer types." (PMID 34361082, 2021). "Nonetheless, Nucb2/nesfatin-1 seems to have an auto-, paracrine and tissue-specific mode of action that could be exploited in the treatment, diagnosis, and monitoring of different types of cancer." (PMID 34073612, 2021). "Additionally, the same research group analyzed whether there was a correlation between Nucb2-regulated cell migration and the significance of Nucb2 in the migration of cancer cells facilitated by the action of matrix metalloproteases MMP-2 and MMP-9." (PMID 34073612, 2021). "The present review is the first to describe NUCB2/NESF-1 as a new prognostic and predictive marker in cancers." (PMID 34361082, 2021). "The summary below gives evidence that suggests that NUCB2/NESF-1 is a potential new biomarker in different cancer types and introduces it as a new area for cancer research." (PMID 34361082, 2021). "Nucleobindin 2 (NUCB2) has been reported to play an important role in both tumorigenesis and cancer progression." (PMID 32221080, 2020). "The analyses revealed that the expression of NUCB2/NESF-1 was significantly higher in cancer cells compared to the noncancerous control." (PMID 34361082, 2021). "Moreover, univariate analysis revealed that NUCB2/NESF-1 status was an independent prognostic factor for disease-free survival and cancer-specific survival." (PMID 34361082, 2021). "In conclusion, NUCB2/NESF-1 might be used as a new biomarker and a potential therapeutic target for different cancer types in the future." (PMID 34361082, 2021). "In addition to its involvement in energy regulation, NUCB2 has been identified as a negative prognostic indicator in several cancer types, including breast cancer, colon cancer, bladder cancer, prostate cancer, endometrial cancer, gastric cancer, papillary thyroid cancer, and renal cell carcinoma." (PMID 37830634, 2023).
metabolic disorders (10 papers, 2014 to 2025). "Since AVP is intrinsically regulates feeding behavior, further clarification of the underlying mechanisms of AVP on nesfatin-1/NucB2 pathway would contribute to the identification of potential therapeutic targets for the treatment of metabolic disorders in the future." (PMID 34134629, 2021).
infection (3 papers, 2013 to 2024). The state of being infected such as from the introduction of a foreign agent such as serum, vaccine, antigenic substance or organism. "A NUCB2 stable knockdown BeWo cell model was successfully established via lentiviral vector infection." (PMID 38339201, 2024).
neurodegenerative disease (1 paper, 2024). A disorder of the central nervous system characterized by gradual and progressive loss of neural tissue and neurologic function. "Thus, under specific conditions, Nucb2/N1 may be involved in the pathogenesis of neurodegenerative diseases since, as both are localized in the brain." (PMID 38812013, 2024).
NUCB2 also shares sentences with these, for which no sentence is quoted: metabolic syndrome (9 papers); gestational diabetes mellitus (7); acute myocardial infarction (6); Impaired glucose tolerance (6); subarachnoid hemorrhage (5); atherosclerosis (4); chronic obstructive pulmonary disease (4); lung carcinoma (4); cardiovascular disease (3); diabetic kidney disease (3); epilepsy (3); Hyperglycemia (3); Hyperinsulinemia (3); hypothyroidism (3); malnutrition (3); psychiatric disorder (3); rheumatoid arthritis (3); Alzheimer disease (2); binge eating disorder (2); bipolar disorder (2); brain injury (2); central precocious puberty (2); chronic kidney disease (2); Cognitive impairment (2); diabetic retinopathy (2); Digestive Diseases (2); endometriosis (2); gastric ulcer (2); glucose metabolic disorders (2); infertile (2).
A further 80 diseases each share a sentence with NUCB2 in 2 papers or fewer.